GPR65 (G protein-coupled receptor 65)
Diseases named in the same sentence as GPR65 in open-access papers (continued):
Sharing a sentence is not in itself a finding about the gene and the disease.
Crohn disease (1 paper, 2018). A gastrointestinal disorder characterized by chronic inflammation involving all layers of the intestinal wall, noncaseating granulomas affecting the intestinal wall and regional lymph nodes, and transmural fibrosis. "Similarly, G protein-coupled receptor 65 (GPR65), a receptor for psychosine and several related glycosphingolipids, received a strong Open Targets score for Crohn’s disease mostly due to its strong genetic association." (PMID 30285606, 2018).
fibrosis (1 paper, 2023). the formation of excess fibrous connective tissue in an organ or tissue in a reparative or reactive process. "The hepatic level of GPR65 was markedly upregulated in the livers of subjects with fibrosis than it was in individuals with normal livers." (PMID 38001521, 2023). "We first examined GPR65 expression in the livers of human subjects without fibrosis, with mild or advanced fibrosis as diagnosed clinically and pathologically." (PMID 38001521, 2023).
gastric cancer (1 paper, 2023). A primary or metastatic malignant neoplasm involving the stomach. "Due to the strong expression of GPR65 we observed in our study, one could speculate that, compared to gastric cancer, at least the PTEN-AKT-slug signaling pathway is activated by GPR65 in peritoneal carcinomatosis of CRC." (PMID 36902589, 2023).
head and neck squamous cell carcinoma (1 paper, 2025). A squamous cell carcinoma that arises from any of the following anatomic sites: lip and oral cavity, nasal cavity, paranasal sinuses, pharynx, larynx, and salivary glands. "It has been found that the acidic microenvironment may induce PD-L1 on cancer cells and thus down-regulate anti-tumor immune responses, while in human Head and Neck squamous cell carcinoma (HNSCC), PD-L1 mRNA expression correlated with GPR65 mRNA expression." (PMID 40519919, 2025).
Hepatic fibrosis (1 paper, 2023). The presence of excessive fibrous connective tissue in the liver. "After 21 d of BDL, we performed RNA-seq to explore the effect of Gpr65 deficiency on BDL-induced hepatic fibrosis." (PMID 38001521, 2023). "To confirm this, we performed HE staining, Sirius red staining, Masson’s trichrome staining and IHC for COL1α1 and α-SMA, and the results revealed that loss of Gpr65 significantly alleviated BDL-induced hepatic fibrosis." (PMID 38001521, 2023). "Here, we aimed to reveal the role of GPR65, a proton-sensing receptor, in liver fibrosis and to elucidate the underlying mechanism." (PMID 38001521, 2023). "Furthermore, Gpr65-deficient mice were treated with either bile duct ligation (BDL) for 21 d or carbon tetrachloride (CCl4) for 8 weeks to investigate the role of GPR65 in liver fibrosis." (PMID 38001521, 2023). "In the present study, we focused our attention on the role and mechanism of proton-sensing receptor GPR65 in hepatic fibrosis." (PMID 38001521, 2023). "To investigate the role of GPR65 in hepatic fibrosis in vivo, we generated GPR65-KO mice and subjected them to sham operation or BDL." (PMID 38001521, 2023). "GPR65 inhibition significantly attenuated CCl4-induced hepatic fibrosis, as evidenced by HE staining, Sirius red staining, Masson’s trichrome staining, IHC, Western blotting and qRT-PCR for pro-fibrogenic genes, as well as liver hydroxyproline content." (PMID 38001521, 2023). "Considering the heterogeneity of hepatic fibrosis, we further examined GPR65 function with a CCl4-induced hepatic fibrosis model." (PMID 38001521, 2023). "Taken together, our results demonstrate that HMs-enriched GPR65 is upregulated in both human and mouse fibrotic livers, suggesting a role of GPR65 in the development of hepatic fibrosis." (PMID 38001521, 2023). "We next explored the therapeutic potential of targeting GPR65 in the development of hepatic fibrosis." (PMID 38001521, 2023). "The hepatic hydroxyproline content in BDL-treated GPR65-KO mice was also markedly decreased compared to BDL-treated WT mice, suggesting that loss of Gpr65 significantly alleviated BDL-induced hepatic fibrosis." (PMID 38001521, 2023). "Additionally, the therapeutic potential of GPR65 inhibitor in the development of liver fibrosis was investigated." (PMID 38001521, 2023). "GPR65 is a major regulator that modulates the progression of liver fibrosis." (PMID 38001521, 2023). "After 8 weeks of CCl4 treatment, we tested whether the inhibition of GPR65 alleviated CCl4-induced hepatic fibrosis in vivo." (PMID 38001521, 2023). "Thus, targeting GPR65 could be an effective therapeutic strategy for the prevention of liver fibrosis." (PMID 38001521, 2023). "Therefore, we believe that F4/80 and LY6C positive cells are decreased in GPR65-KO mice after BDL and CCl4 treatment may be a result of reduced recruited macrophage or the consequence of decreased liver fibrosis." (PMID 38001521, 2023).
kidney tumor (1 paper, 2025). "An earlier study found that GPR65 was overexpressed in colon, ovarian and kidney tumor tissues." (PMID 40519919, 2025).
Obesity (1 paper, 2025). Accumulation of substantial excess body fat. "This is further supported by a murine model that found that macrophage infiltration in obesity-associated colorectal and hepatocellular cancers promoted tumour growth, and that this was associated with elevated GPR65 expression in the TAMs of the subjects with obesity." (PMID 41375084, 2025).
osteoarthritis (1 paper, 2024). A noninflammatory degenerative joint disease occurring chiefly in older persons, characterized by degeneration of the articular cartilage, hypertrophy of bone at the margins and changes in the synovial membrane. "Stimulation of GPR65 on human FLS also triggered the release of inflammatory mediators and synovial fluid samples from human osteoarthritis patients were shown to activate GPR65." (PMID 39661058, 2024). "Furthermore, synovial fluid samples from human osteoarthritis patients activated GPR65." (PMID 39661058, 2024).
Sepsis (1 paper, 2025). Sepsis is defined as life-threatening organ dysfunction caused by a dysregulated host response to infection. "CD19 and GPR65 were identified as key genes associated with sialylation in sepsis-induced ARDS." (PMID 40375981, 2025). "Thus, CD19 and GPR65 were recorded as key genes associated with sialylation in sepsis-induced ARDS." (PMID 40375981, 2025). "We identified CD19 and GPR65 as key genes associated with sialylation in sepsis-induced ARDS, highlighting CD14Mono as key cell type implicated in sepsis-induced ARDS." (PMID 40375981, 2025). "GSEA was implemented to probe the specific signaling mechanisms of CD19 and GPR65 in sepsis-induced ARDS." (PMID 40375981, 2025). "Our preliminary research indicates that CD19 and GPR65 are key sialylation-related genes in sepsis-induced ARDS, with CD19 upregulated and GPR65 downregulated in ARDS patients." (PMID 40375981, 2025). "The nomogram model we constructed demonstrated that CD19 and GPR65, when considered jointly, exhibited strong predictive power for sepsis-induced ARDS." (PMID 40375981, 2025). "Single-cell sequencing revealed significant differences in CD19 and GPR65 expression in CD14Mono cells between ARDS and sepsis groups, with GPR65 showing an initial increase, then decrease, and a subsequent increase during differentiation." (PMID 40375981, 2025). "The constructed nomogram model demonstrated that CD19 and GPR65 as a whole exhibited robust predictive capability for sepsis-induced ARDS." (PMID 40375981, 2025). "This study identified CD19 and GPR65 as key sialylation-related genes in sepsis-induced ARDS through bioinformatics analyses." (PMID 40375981, 2025). "Our study found significant upregulation of CD19 and downregulation of GPR65 in sepsis-induced ARDS patients, suggesting they could be new therapeutic targets for this condition." (PMID 40375981, 2025). "The expression trend of GPR65 remained consistent with the public database, yet it did not exhibit statistically significant differences in the sepsis and ARDS groups (P < 0.05)." (PMID 40375981, 2025).
serous ovarian carcinoma (1 paper, 2018). "High expression of both GPR65 and FFAR4 significantly correlated with lower survival in patients with serous ovarian carcinoma." (PMID 29712888, 2018).
skin tumors (1 paper, 2020). "In this study, we have examined the expression profiles of the pH-GPCRs GPR4 (GPR19), TDAG8 (GPR65), OGR1 (GPR68) and G2A (GPR132) on different types of common skin tumors, SCC, MM, NCN and BCC." (PMID 32948783, 2020).
tumor (33 papers, 2013 to 2026). "GPR65 deficiency increased vascular endothelial growth factor A (VEGFA) production in tumor cells, which expanded macrophages and skewed them toward an M2-like immunosuppressive phenotype." (PMID 41152975, 2025). "Beyond tumor cells, GPR65 is highly expressed on immune populations such as tumor-associated macrophages (TAMs)." (PMID 41152975, 2025). "Through single-cell network analyses, we discovered that GPR65 deficiency reshapes tumor interactions with host macrophages by increasing tumor VEGFA levels, leading to macrophage expansion and preferential M2 polarization." (PMID 39998425, 2025). "It was shown that GPR65 sensed tumor acidosis to induce the polarization of tumor-associated macrophages (TAMs) towards a non-inflammatory phenotype and immunoevasion." (PMID 39336742, 2024). "In summary, GPR65 on tumor-associated macrophages responds to lactate stimulation, leading to HMGB1 secretion through the cAMP-PKA-CREB signaling pathway." (PMID 38576043, 2024). "Further analysis of the molecular role and mechanism of GPR65 in OS patients revealed that GPR65 is mainly associated with tumor immunity in patients." (PMID 38218960, 2024). "Based on these findings, we studied primary human T-cells and showed that GPR65 agonism inhibited the functions of T-cells stimulated with tumour-associated antigens." (PMID 39483470, 2024). "Mice with GPR65 KO tumors had a higher tumor burden in all organs examined than mice with m.CR tumors, and this was associated with increased tumor-associated morbidities and diminished survival." (PMID 39998425, 2025). "Similar to the DKO tumors, the response of GPR65 KO tumors was incomplete, with mice ultimately succumbing to the tumor." (PMID 39998425, 2025). "That VEGFA and GPR65 DKO tumors show restoration of CAR T susceptibility and that this reduces the TME macrophage number and tumor burden implicate tumor-produced VEGFA as a key mediator of CAR T resistance in the B-ALL system." (PMID 39998425, 2025). "Tool molecules designed by Pathios to inhibit GPR65, PTT-3196, and PTT-3213 have been used to explore the effects of selective GPR65 inhibition in tumours." (PMID 41375084, 2025). "Preclinical studies demonstrate that GPR65 antagonists restore anti-tumour immune activity by reversing acidosis-driven immunosuppression and enhancing antigen processing." (PMID 41375084, 2025). "Following on from the preclinical data generated using PTT-3213 and PTT-3196 in RCC-derived tumour models, Pathios has taken an optimised, lead candidate of its GPR65 inhibitor into the clinic." (PMID 41375084, 2025). "In particular, GPR65 emerges as an important proton-sensing receptor in cancer biology, exhibiting both tumour-promoting and tumour-suppressive functions depending on cellular context and cancer type." (PMID 41375084, 2025). "VEGFA was, as expected, elevated in GPR65 KO compared with m.CR tumor cells and was significantly diminished after FOXO1 KO." (PMID 39998425, 2025). "Relative to tumor-free mice, CAR T cells from mice with either m.CR or GPR65 KO tumors upregulated genes associated with exhaustion." (PMID 39998425, 2025). "Pan-cancer analysis reveals variable GPR65 expression patterns across different tumour types, with significant correlations between expression levels and patient prognosis." (PMID 41375084, 2025). "Comparative analysis of the m.PR and m.CR tumor cells at baseline by RNA sequencing (RNA-seq) identified the G protein–coupled receptor (GPCR) Gpr65 (Tdag8) among the top upregulated genes in CR tumors." (PMID 39998425, 2025). "In our in vivo model, m.CR and GPR65 KO tumors showed similar growth rates, with similar tumor burden at the time of CAR T-cell treatment." (PMID 39998425, 2025). "Collectively, these findings support a mechanistic role for GPR65 in tumour survival, immune modulation, and progression within the context of RCC." (PMID 41375084, 2025).
tumor (continued). "In tumor cells, GPR65 activation promotes survival and proliferation by engaging cAMP/ protein kinase A (PKA) and MAPK signaling, thereby enhancing adaptability to acidic stress and driving tumor progression." (PMID 41152975, 2025). "Clustering of tumor cells revealed that GPR65 KO and m.CR tumors were distinct with further divergence after CAR T-cell treatment." (PMID 39998425, 2025). "Next, we isolated transferred CAR T cells 4 days after treatment of m.CR or GPR65 KO tumor–bearing mice and then retransferred these T cells into new mice with established m.CR tumors." (PMID 39998425, 2025). "In vitro analyses of GPR65 KO and m.CR tumor cells demonstrated equivalent sensitivity to killing, arguing against an intrinsic resistance to lysis among GPR65 KO tumor cells." (PMID 39998425, 2025). "Collectively, GPR65 emerges as a key regulator of tumor–immune interactions and a promising therapeutic target in the acidic TME." (PMID 41152975, 2025). "Depletion of host macrophages or VEGF blockade completely restores the sensitivity of GPR65 KO tumor–bearing mice to anti-CD19 CAR T-cell therapy." (PMID 39998425, 2025). "In obesity-driven cancer models, oleic acid accumulation creates an acidic milieu that is sensed by TAMs via GPR65, promoting their polarization toward a protumorigenic state and accelerating tumor growth." (PMID 41152975, 2025). "To determine the relevance of GPR65 in human tumor responses, we analyzed data from a clinical trial of CD19 CAR T treatment of patients with B-ALL and patients treated with blinatumomab." (PMID 39998425, 2025). "Integrative and cross-species systems biology and in vivo modeling identifies tumor-intrinsic GPR65 as a regulator of macrophage-driven CAR T-cell resistance and a translational biomarker for CAR T-cell response in B-ALL." (PMID 39998425, 2025). "Analyses of TME RNAseq datasets have also established that monocytes, macrophages, CD8+ T-cells, and NK cells are the most frequent GPR65-expressing tumour-infiltrating cells—all known to play critical roles in cancer immunity." (PMID 41375084, 2025). "Mechanistic evidence from peer-reviewed studies implicates GPR65 as a modulator of cancer progression via the promotion of tumour cell adaptation to acidosis, conferring resultant survival benefits and immune evasion." (PMID 41375084, 2025). "It has been shown that GPR65 can enhance tumor progression by promoting the adaptation of cancer cells to an acidic environment and by facilitating cell survival and proliferation." (PMID 40519919, 2025). "Consistently, DKO tumors had fewer tumor cells and macrophage numbers compared with GPR65 KO tumors 4 days after treatment." (PMID 39998425, 2025). "We observed an adaptive response with expansion of the macrophage population induced by CAR T treatment in both m.CR and GPR65 KO tumor–engrafted mice." (PMID 39998425, 2025). "GPR65 KO tumors expressed increased TFs of the AP-1 family (Fos and Fosb) and the antiapoptotic marker Bcl2, known to promote tumor cell survival." (PMID 39998425, 2025). "We implicate tumor expression of the G protein–coupled receptor 65 (GPR65; TDAG8) in antigen-independent CAR T-cell resistance." (PMID 39998425, 2025). "GPR65 is an extracellular pH-sensing G protein-coupled receptor and a glycosphingolipid receptor, which is engaged in the functions of regulating tumor immunity." (PMID 40519919, 2025). "This identified Foxo1 among the top three TFs upregulated in GPR65 KO compared with m.CR tumor cells." (PMID 39998425, 2025). "Our research identified G protein–coupled receptor 65 (GPR65) as a tumor-specific determinant affecting the efficacy of CAR T-cell therapy." (PMID 39998425, 2025). "Our observation that GPR65 KO tumor–bearing mice display a higher disease burden in all organs, suggesting potential extramedullary disease, is consistent with the published findings." (PMID 39998425, 2025).